G6PD (glucose-6-phosphate dehydrogenase)
Diseases named in the same sentence as G6PD in open-access papers (continued):
Sharing a sentence is not in itself a finding about the gene and the disease.
malaria (continued). "After validation, the multiplexed HRM assay was applied to screen G6PD mutations of 725 people living in a malaria endemic area along the Thai–Myanmar border." (PMID 33879156, 2021). "POC testing for glucose-6-phosphate dehydrogenase (G6PD) deficiency represents another significant transformation in malaria case management." (PMID 34238299, 2021). "Of these, 78% (511/657) were eligible for IPTp-SP after excluding women who have less than 16 weeks of gestation, G6PD deficient, malaria positive and have taken 5 doses of IPTp-SP prior to day of observation." (PMID 34610842, 2021). "The distribution and selection of genetic variants of the G6PD gene in malaria-endemic regions and its associated protection against severe malaria remain controversial." (PMID 34570821, 2021). "Above bioinformatics analysis showed that G6pd deficiency prevents the host’s immune response during malaria." (PMID 34456927, 2021). "Glucose-6-phosphate dehydrogenase (G6PD) deficiency that is heterogeneously associated with malaria protection and thus highly prevalent in malaria-endemic areas, appears to be negatively correlated with the SCT in some populations; in India for instance." (PMID 33461216, 2021). "Understanding the hemolytic risk of 8-aminoquinolines for G6PD-deficient patients is critical for safe and effective malaria treatment, which necessitates detailed knowledge of the patients G6PD mutation(s) and symptoms." (PMID 34934109, 2021). "Drug-induced hemolysis has raised serious concerns regarding malaria elimination because antimalarials, such as 8-aminoquinolines, have been linked to hemolytic anemia in G6PD-deficient individuals." (PMID 34934109, 2021). "Generally, to avoid the risk of haemolysis upon malaria treatment, G6PD testing is recommended before the administration of primaquine and tafenoquine." (PMID 33879156, 2021). "This is particularly true for malaria–despite the known association of G6PDd with PQ for over 60 years qualitative point-of-care (POC) G6PD diagnostics have only recently become available, and use remains limited in many areas." (PMID 34899347, 2021). "The severe Mediterranean variant (G6PD Med) found across Europe and Asia is thought to confer protection against malaria, but its effect is unclear." (PMID 33543710, 2021). "Our findings provide a novel perspective of the underlying mechanism of G6PD deficiency mediated protection against malaria in vivo." (PMID 34456927, 2021). "The odds of detecting malaria microscopically among the glucose-6-phosphate dehydrogenase genotypic variants." (PMID 34570821, 2021). "In previous studies, it was suggested an underlying mechanism for the G6PD deficiency-mediated protection against malaria and found that G6PD-deficient monocytes intensify the phagocytosis of ring-parasitized variant RBCs due to enhanced oxidative stress." (PMID 34456927, 2021). "In this study, we used a G6pd-deficient mice infected with the rodent parasite Plasmodium berghei (P.berghei) to set up a malaria model in mice." (PMID 34456927, 2021). "Primaquine has been recommended for the treatment of P. falciparum gametocytes and P. vivax hypnozoites, however, its implementation is challenged by the high prevalence of G6PD deficient (G6PDd) genotypes in malaria endemic countries." (PMID 34570821, 2021). "G6PD provides instructions for the production of a glucose-6-phosphate dehydrogenase enzyme and its deficiency is related to malaria resistance." (PMID 32986826, 2021). "Because of the risks associated with G6PD deficiency and primaquine use, the malaria treatment guidelines of the World Health Organization (WHO) recommend that “the G6PD status of patients should be used to guide administration of primaquine”." (PMID 34238299, 2021). "Since the anti-malaria drug primaquine has been early linked with acute hemolysis in G6PD deficient subjects, we treated Fyn-/- mice with primaquine." (PMID 32863204, 2020).
malaria (continued). "Even though a prospective study would have been important in determining the effect of inherited blood disorders on malaria, this cross-sectional study demonstrated association between ABO, G6PD and haemoglobin type on malaria in Kenyan children." (PMID 32646433, 2020). "This is analogous to a hypomorphic allele of the human G6PD gene, which encodes an enzyme in the pentose phosphate pathway and features a long haplotype because of selection for malaria resistance." (PMID 32514036, 2020). "About 400 million people are estimated to be G6PD deficient worldwide, with a geographical distribution similar to that of malaria but also with high variability within countries and regions." (PMID 32787970, 2020). "Median G6PD activities between ethnicities were compared and the association between G6PD activity and malaria status was assessed." (PMID 32925910, 2020). "This combined with the drive to eliminate malaria, is encouraging malaria-endemic countries to increase access to testing for glucose-6-phosphate dehydrogenase (G6PD) deficiency." (PMID 32766454, 2020). "Genetic diversity of ABO blood, glucose-6-phosphate dehydrogenase (G6PD) deficiency and haemoglobin type and their ability to protect against malaria vary geographically, ethnically and racially." (PMID 32646433, 2020). "Arachidonic acid inhibits G6PD generation and it is well known that G6PD deficiency protects against malaria." (PMID 34532222, 2020). "Although G6PD‐deficient alleles appear to confer a protective effect of malaria, the link with clinical protection against Plasmodium infection is conflicting." (PMID 31872983, 2020). "Some informants mentioned they felt it necessary to revise the national guidelines for malaria diagnosis and treatment to explicitly include G6PD diagnostic testing in routine malaria service." (PMID 33396538, 2020). "The view that G6PD deficiency has risen to high frequency in malaria‐endemic regions because of the resistance to malaria was proposed over half a century ago and is now widely accepted." (PMID 31872983, 2020). "Taken together, variations in reports in the association between red blood cell, haemoglobin, and G6PD type with malaria disease progression shows the complexity of interaction between parasite and host genetics and immunity factors." (PMID 32646433, 2020). "In Mali, hemizygous G6PD (A−) condition in the male while sickle cell trait in female children is associated with protection against severe malaria anaemia." (PMID 32646433, 2020). "The association between glucose-6-phosphate dehydrogenase [G6PD] deficiency and severe malaria is less clear." (PMID 31941490, 2020). "Carriage of the heterozygous G6PD type compared to the normal G6PD is associated with risk of severe malaria anaemia." (PMID 32646433, 2020). "Specifically, the study examined factors of importance for the implementation of the novel G6PD diagnostic tool including local people’s perceptions, health-seeking behaviors, and treatment adherence related to malaria." (PMID 33396538, 2020). "Considering the high number of P. vivax infections found in these populations, there is a need for further evaluation of the frequency of G6PD deficiency in malaria-endemic areas in view that the primaquine treatment (14 days) is required for the radical cure." (PMID 32299449, 2020). "Considering the recent case reports of G6PD deficiency-mediated haemolytic anaemia in this malaria-endemic area and the implementation of military malaria chemoprophylaxis, ultimately, screening for deficiency prior to primaquine administration is essential." (PMID 32873296, 2020). "To investigate this, we estimated the effect of G6PD status on pneumococcal bacteremia risk as malaria transmission declined over the period of the study." (PMID 32536341, 2020). "Glucose-6-phosphate dehydrogenase (G6PD) deficiency is currently a threat to malaria elimination due to risk of primaquine-induced haemolysis in G6PD deficient individuals." (PMID 32787970, 2020).
malaria (continued). "Consistent with expectations for a locus that protects against malaria mortality, estimates of the G6PD A− 202A and 376G alleles were generally consistent with the distribution of endemic malaria across the continent." (PMID 33116287, 2020). "First, sample sizes were small for certain groups, notably the SS and G6PD homozygous genotypes, which limited the ability to evaluate their associations with malaria outcomes." (PMID 31941490, 2020). "G6PD is essential for the protection of cells against oxidative damage and G6PD deficiency is common in malaria endemic areas due to its association with protection of some manifestations of severe malaria." (PMID 30665411, 2019). "The mutation A376G that constitutes G6PD*A- variant accounted for nearly 23% of the malaria patients." (PMID 31590661, 2019). "By selection, this G6PD-deficient trait becomes prevalent (8%) in populations where malaria is endemic." (PMID 31590661, 2019). "Among a subset of 202 febrile patients who were diagnosed with malaria, 11 (5.45%) were G6PD-deficient." (PMID 31590661, 2019). "Radical cure of Plasmodium vivax malaria in glucose-6-phosphate dehydrogenase (G6PD) deficient individuals employs weekly primaquine dosing." (PMID 31069260, 2019). "Of these 158 malaria patients, the mutation frequency of the three G6PD gene positions (A376G, G267 + 119C-T, and G1116A) ranged from 0.6 to 4.4%." (PMID 31590661, 2019). "The mild and most common mutations result in reduced G6PD activity, and their protective effect against malaria is most likely based on enhanced phagocytosis of parasitized G6PD-deficient erythrocytes." (PMID 30683097, 2019). "The aim of this study was to detect the prevalence of G6PD Viangchan deficiency in malaria endemic areas in Phongsaly, Savannakhet, and Champasak provinces in Lao PDR." (PMID 30866940, 2019). "Of the 158 patient samples (95 males and 63 females) that were diagnosed with malaria, 11 (6.9%) were considered as G6PD deficient." (PMID 31590661, 2019). "As expected, most recruited patients were young male farmers, an important risk group in the GMS, so our data are applicable to other GMS countries with moderately severe G6PD variants and a similar malaria epidemiological characteristics as Cambodia." (PMID 30871496, 2019). "The prevalence of some common human mutations selected by malaria such as G6PD deficiency variant Viangchan, Haemoglobin E and Haemoglobin Constant Spring were measured in the general population and in malaria patients." (PMID 30939179, 2019). "Clinical impact of anti-malaria drugs other than PQ in individuals with different G6PD variants is currently unclear." (PMID 29548282, 2018). "Of these 50 malaria patients with G6PD variants, 25 (50.0%), 17 (34.0%), and 8 (16.0%) were infected with P. falciparum, P. vivax, and co-infections with both P. falciparum and P. vivax, respectively." (PMID 29548282, 2018). "The risk of haemolytic toxicity of PQ in individuals with genetic deficiency of G6PD, which constitutes a significant proportion in malaria endemic countries, is a major concern." (PMID 30103751, 2018). "Polymorphisms that alter the sequence of hemoglobin, decrease hemoglobin production, or decrease the activity of G6PD have been associated with changes in malaria risk, but results from a range of studies have varied." (PMID 30222732, 2018). "That flaw threatens the approximately 400 million G6PD-deficient people globally, representing about 8% of people living in malaria endemic countries, with a potentially life-threatening acute haemolytic anaemia at therapeutic hypnozoitocidal doses." (PMID 29357870, 2018). "This study aimed at molecular characterization and determination of the prevalence of common G6PD variants, namely, B, A, A- and Mediterranean, in microscopically diagnosed malaria patient Eritrean ethnic groups." (PMID 30918572, 2018). "Six different types of G6PD allelic variants were identified in 50 (7 females and 43 males) malaria patients." (PMID 29548282, 2018).
malaria (continued). "The prevalence of the normal G6PD B allele was 87.5% (272/311) among the malaria patients, which is in line with the literature that the wild type G6PD B allele is the most common variant in Africa and worldwide." (PMID 30918572, 2018). "The historical background to these recommendations and the current primaquine and G6PD deficiency testing policies in malaria-endemic countries are reviewed briefly here." (PMID 29672516, 2018). "This is the first study performed to genotype and determine the prevalence of four common G6PD variants by PCR-RFLP in microscopically confirmed malaria patients living in five zobas of Eritrea." (PMID 30918572, 2018). "Fifty out of 252 malaria patients (215 males and 37 females) analyzed in this study had at least one of G6PD variants." (PMID 29548282, 2018). "Of the 39 genotyped malaria patients with G6PD A variant, 15 (4.8%) were A heterozygous females (type AB), 1 (0.3%) was an A homozygous female (type AA), and 23(7.4%) were A hemizygous males (type A)." (PMID 30918572, 2018). "The procurement logistics and long therapy duration with primaquine, the need for pre-treatment G6PD screening, in an Eritrean population with an allele prevalence of 3–7% dictate that a specific policy is needed to address malaria in Eritrean migrants." (PMID 30497487, 2018). "The G6PD multiplex allele specific PCR analysis of 252 blood samples revealed several types of G6PD variants in 50 malaria patients." (PMID 29548282, 2018). "Whereas homozygosity is necessary for affecting the host’s response in HIV and HCV, in severe malaria heterozygous, deficiency for G6PD gives advantages and the homozygous leads to disadvantages." (PMID 30180856, 2018). "Molecular findings and prevalence of G6PD variants: the PCR-RFLP analysis showed that 272 (87.5%) out of 311 clinically determined malaria patients carried the normal G6PD allele and 39 (12.5%) the G6PD A(A376G) variant." (PMID 30918572, 2018). "Studies of associations between the G6PD A- genotypeand severe malaria have been less consistent than for the other studied polymorphisms, with reports of protective effects in females, in males, in both, or no protection." (PMID 30222732, 2018). "This study is the first report on molecular characterization and the prevalence of G6PD allelic variants in microscopically confirmed malaria patients in Eritrea." (PMID 30918572, 2018). "Glucose 6-phosphate dehydrogenase (G6PD) deficiency is the most common enzymopathy with a relatively high frequency in malaria-endemic regions." (PMID 30918572, 2018). "A case-control study showed significant association between G6PD A- and risk of severe malaria, with protection against cerebral malaria, but increased risk of severe anemia." (PMID 30222732, 2018). "The overall prevalence of G6PD A variant was 12.5% observed in the analyzed microscopically diagnosed malaria patients." (PMID 30918572, 2018). "At the Thailand–Myanmar border, as in many malaria-endemic locations, extended breastfeeding and G6PD deficiency are common, and G6PD testing is often unavailable." (PMID 29590311, 2018). "The study provides a database for G6PD 563c.C>T variance in Southern Pakistan demonstrating presence of this variant in patients suffering from malaria." (PMID 29065882, 2017). "Recent studies suggest that by reducing levels of parasitemia, the selection of G6PD mutations has also been driven by P. vivax, the other major cause of human malaria." (PMID 28591790, 2017). "Glucose-6-phosphate dehydrogenase (G6PD) deficiency is the most common enzymatic disorder in humans and appears to be protective against falciparum severe malaria." (PMID 28591790, 2017). "The geographical distribution (prevalence in general) of malaria closely resembles the global distribution of deficient G6PD variants." (PMID 28535765, 2017).
malaria (continued). "In Sri Lanka, especially in Anuradhapura and Kurunegala, malaria has been a life threatening occurrence for centuries, and it is to be expected that normal individuals would be selected against by malaria and G6PD deficient individuals would be favoured." (PMID 28152025, 2017). "The malaria-protective effect of PK-deficiency is phenotypically similar to that of inactivation of other erythrocyte proteins (G6PD, Band-3, DARC), including hemoglobin (sickle cell anemia, thalassemias)." (PMID 28542307, 2017). "Another study from Tanzania found mean hemoglobin reductions of roughly 8% among both G6PD deficient and normal volunteers with smear-positive malaria treated with artemether-lumefantrine (AL) and low dose primaquine." (PMID 28591198, 2017). "Malaria drugs such as primaquine, sulfanilamide, and sulfadoxine have been reported to cause hemolysis in G6PD-deficient individuals." (PMID 28583873, 2017). "Malaria is the evolutionary driving force behind sickle-cell disease (HbS), thalassemia, glucose-6-phosphatase deficiency (G6PD) and other erythrocyte defects that together comprise the most common Mendelian diseases of humankind." (PMID 28469196, 2017). "We obtained questionnaire data on demographics, behaviour, and residential malaria risk factors, and we also assessed glucose-6-phosphate dehydrogenase (G6PD) enzyme activity." (PMID 28758162, 2017). "Glucose-6-Phosphate Dehydrogenase (G6PD) deficiency overlaps with malaria endemicity although it predisposes carriers to hemolysis." (PMID 28382932, 2017). "The interviews were analysed with regard to respondents perceptions of vivax malaria, -primaquine based treatment for malaria and the complexities of G6PD deficiency." (PMID 28797255, 2017). "The genetically normal but phenotypically deficient individual was diagnosed positive for malaria by RDT at the time of G6PD screening (June 2015)." (PMID 28376871, 2017). "Although there is a large body of circumstantial evidence to suggest that G6PD deficiency confers resistance to malaria, there has been much debate about the precise nature of the protective effect." (PMID 28067620, 2017). "A non-synonymous G6PD mutation known to be associated with deficiency was found in three malaria patients (4.8%), all recruited within the randomized study." (PMID 28356147, 2017). "A cohort study reported the effect of primaquine treatment on female patients with malaria carrying G6PD Mahidol, a mild G6PD variant that is common in Southeast Asia." (PMID 28583873, 2017). "Mean (± SD) haemoglobin, median (IQR) platelet and median (IQR) parasite count in G6PD-deficient malaria-patients were 8.9 ± 0.9 g/dL, 124 × 109/L (IQR 32, 171) and 57,920/μL of blood (IQR 12,920, 540,000) respectively." (PMID 29065882, 2017). "It is postulated that increase in G6PDd has been associated with the natural selection of G6PD deficient variants which confers protection or resistance against malaria caused by Plasmodium falciparum and Plasmodium spp." (PMID 28535765, 2017). "If PQ is considered for inclusion in malaria control programs, safety studies are needed with PQ at doses within the therapeutic range in G6PD deficient individuals." (PMID 27825738, 2016). "For example, G6PD has been associated with favism caused by G6PD deficiency that can affect survival of the malaria parasite, Plasmodium falciparum." (PMID 27042214, 2016). "Development of effective hypnozoitocidal drugs for preventing P. vivax relapses and offering safety in G6PD-deficient patients is a key research priority when considering malaria elimination and eventual eradication." (PMID 27430544, 2016). "Variation in the enzyme activity of G6PD deficiencies has an impact on malaria treatment, because antimalarials such as primaquine, sulfanilamide and sulfadoxine have been observed to cause hemolysis in G6PD deficient individuals." (PMID 27053284, 2016).